GAS5 (growth arrest specific 5)
Diseases named in the same sentence as GAS5 in open-access papers (continued):
Sharing a sentence is not in itself a finding about the gene and the disease.
tumor (continued). "In particular, previous studies indicated that GAS5 interacts with miR-222, miR-106b, miR-135a, miR-21 and miR-205, conferring tumor suppressor properties and induction of sensitivity to chemo- and radiotherapy." (PMID 33076450, 2020). "The interesting finding was that corylin was found to exert such effects on tumor growth through activation of GAS5." (PMID 33076450, 2020). "GAS5 is located on chromosome 1q25, comprising twelve exons and playing an important role in carcinogenesis as a tumor suppressor." (PMID 32435497, 2020). "In various types of tumors, decreased expression of GAS5 is significantly associated with clinicopathological features such as TNM stage, histological grade, tumor size and distant metastasis." (PMID 33371204, 2020). "For lncRNA GAS5 (growth arrest-specific transcript 5), a tumor-suppressing function and a role in the inhibition of OvCa progression have also been shown." (PMID 33238475, 2020). "GAS5 has been widely studied in the field of cancer research where it acts as tumor suppressor by regulating cell cycle arrest and cell death." (PMID 32967315, 2020). "Tumor node stage (TNM), overall survival (OS), disease-free survival (DFS), and metastasis were correlated with GAS5 expression, indicating that GAS5 can be a potential diagnostic and prognostic biomarker in HCC." (PMID 32937886, 2020). "Overall, GAS5 acts as a tumor suppressor, whose down-regulation is directly connected to tumor progression, tumor cell proliferation and therapy-related resistance across different types of tumors." (PMID 33076450, 2020). "GAS5 down-regulation was found to be related to high miR-196-5p expression, which induced tumor cell proliferation and progression." (PMID 33076450, 2020). "In the case of miR-18a, it was reported that GAS5 directly binds to it, inhibiting tumor growth via the stimulation of the activity of natural killer (NK) cells." (PMID 33076450, 2020). "The qPCR results revealed that GAS5 was expressed at low levels in tumour tissues compared to peritumoral tissues." (PMID 32661236, 2020). "Yet, all the present studies agree that GAS5 functions as a tumor suppressor and inhibits tumor proliferation, invasion, metastasis and migration." (PMID 33076450, 2020). "Yet, there are some interesting reports suggesting that GAS5 plays a synergistic role in the anti-tumor action of flavonoids and phytochemicals." (PMID 33076450, 2020). "LncRNA GAS5 has been indicated to function as a tumor-inhibitor lncRNA, due to its role in stimulating growth arrest as well as apoptosis." (PMID 32308561, 2020). "After injecting cisplatin, the tumour volume in the lentivirus-GAS5 group even showed a declining trend, while the tumour volume in the lentivirus-NC group increased." (PMID 32661236, 2020). "Several investigations demonstrated that lncRNA GAS5 can act as a tumor suppressor gene by different actions." (PMID 32727450, 2020). "LncRNAs GAS5 is generally identified as a tumor suppressor involved in various type of human cancers, but reports suggest that GAS5 has the ability to promote cancer." (PMID 32354045, 2020). "GAS5 expression levels are inversely correlated with tumor size, staging, and also metastasis in different tumor types, including breast, bladder, colon, pancreas, and prostate cancer." (PMID 33142861, 2020). "In contrast to GAS5, miR-21 was highly expressed in tumour tissues compared to peritumoral tissues, while the trend in PDCD4 expression was the same as that in GAS5 expression." (PMID 32661236, 2020). "It was also reported that GAS5 exosomes are the basic vehicle of transmission conferring tumor inhibition." (PMID 33076450, 2020). "In sharp contrast, the tumours in the lentivirus-GAS5 group were invisible at the eighth week in vivo." (PMID 32661236, 2020). "The authors enforced GAS5 expression, provoking a significant reduction in tumor growth rate and apoptosis after Adriamycin treatment." (PMID 32850327, 2020).
tumor (continued). "The lncRNA growth arrest-specific 5 (GAS5) plays a significant tumor suppressor role not only in PC but also in various other cancers." (PMID 32042268, 2020). "Our present data provide evidence supporting the proposition that decreased mRNA expression levels of GAS5 in tumor tissues have a decreased overall specific survival in female BLCA patients." (PMID 32354045, 2020). "Upregulation of growth arrest special 5 (GAS5) has turned out to shrink tumor growth by its key downstream mediator insulin-like growth factor 1 receptor (IGF-1R)." (PMID 32122355, 2020). "In the case of miR-544, GAS5 negatively regulates its expression, inhibiting tumor cell proliferation." (PMID 33076450, 2020). "In OC, GAS5 has been shown to inhibit tumor growth and inversely correlate with cisplatin resistance." (PMID 32854207, 2020). "Many studies have shown that GAS5 is mainly used as a tumor suppressor involved in cell proliferation, apoptosis, cell migration and invasion." (PMID 30606744, 2019). "Meanwhile, the expression level of GAS5 was correlated with tumor size, histological grade, and TNM stage in CRC." (PMID 30902880, 2019). "The author believes that the relationship between GAS5 and tumor resistance to chemotherapeutic drugs is a very important research direction." (PMID 30606744, 2019). "In HCCs, GAS5 acts as a tumor suppressor through the negative regulation of miR-21 and its target PDCD4 to suppress the migration and invasion of cancer cells." (PMID 31620370, 2019). "lncRNA GAS5 expression is lower in tumor cells compared to normal cells; its over-expression inhibits tumor cell proliferation and migration while treatment with PI3K activator reduces the inhibitory effects." (PMID 30782187, 2019). "After transfection of pcDNA GAS5, the cell viability of the tumor cells was significantly reduced, the percentage of apoptosis was significantly increased, and the tumor weight was significantly reduced." (PMID 30606744, 2019). "GAS5 expression in human tumor cells is relatively low compared to normal tissues, consistent with the idea that GAS5 exerts an anti-proliferative, tumor suppressing phenotype." (PMID 31533355, 2019). "In drug-resistant tumor cells, GAS5 mRNA levels were significantly decreased, and miR-181c-5p expression was increased in drug-resistant cells, and there was a negative correlation between them." (PMID 30606744, 2019). "Whereas overexpression of YAP resulted in dramatically accelerated tumor growth and increased tumor volume and significantly reversed the tumor suppression effect of GAS5 overexpression." (PMID 31619268, 2019). "Generally, higher expressions of GAS5 were usually accompanied by lower expressions of YAP and YTHDF3, while lower expressions of GAS5 were associated with elevated expressions of YAP and YTHDF3 in tumor tissues from CRC patients." (PMID 31619268, 2019). "Low GAS5 expression was found in BC samples and it was considered a distinct tumor suppressor that prevented the glucocorticoid receptor from binding to the target DNA." (PMID 31406486, 2019). "Again consistent with its tumor-suppressor role, GAS5 transcription was found to be higher in adjacent ‘normal’ tissue than in the tumor cells probed." (PMID 31533355, 2019). "The apparent discrepancy between the tumor suppressive function of GAS5 and GAS5-mediated translational upregulation of the oncogene YBX1 remains unanswered and also warrants further study." (PMID 31632972, 2019). "Together, these results clearly show that the expressions of GAS5 are reduced in CRC tissues compared with adjacent tissues, and lower GAS5 expressions are associated with elevated expressions of YAP and YTHDF3 in tumor tissues from CRC patients." (PMID 31619268, 2019). "The GAS5 story has drawn in contributions from prominent molecular geneticists who attempted to define its tumor suppressor function in mechanistic terms." (PMID 31533355, 2019).
tumor (continued). "We found that expressions of GAS5 were lower in tumor tissues compared with their normal mucosal counterparts." (PMID 31619268, 2019). "When injected into nude mice, the tumor size and weight of stably expressing GAS5 groups were all remarkably lessened than the control groups 4 weeks after injection, and GAS5 overexpression groups seems more sensitive to DDP compared with control group." (PMID 31391118, 2019). "GAS5 has been regarded as a tumor suppressor in NSCLC whose expression was significantly lower in tumoral tissues compared with ANCTs." (PMID 30866866, 2019). "Although most people think that GAS5 is a tumor suppressor lncRNA, there are still some reports that GAS5 has the effect of promoting tumor proliferation." (PMID 30606744, 2019). "The long noncoding RNA Growth Arrest Specific Transcript 5 (GAS5) is an identified tumour suppressor involved in several cancers." (PMID 30853980, 2019). "By analysing GAS5 level and clinical parameters, it has been found that GAS5 correlates with tumour progression and poor prognosis in many tumour types." (PMID 30853980, 2019). "In patients with LGG, higher GAS5 expression was significantly correlated with higher tumour purity." (PMID 30853980, 2019). "In BC cells and xenografts mouse models, miR-221/222 inhibits the expression of GAS5 to promote cell proliferation, suppresses cell apoptosis, and increases tumor growth in vivo." (PMID 31480503, 2019). "When a tumor suppressor, such as GAS5, is reported as important in many cancers, the implication is that there are common mechanisms to anchor both research and treatment." (PMID 31533355, 2019). "The lower expression of GAS5 is highly related to big tumor volumes, low histological scores and late TNM stages." (PMID 31572428, 2019). "Other publications on the lncRNA GAS5 address not only proliferation but cell migration and tumor cell invasion." (PMID 31533355, 2019). "In this regard, GAS5 down-regulation is common in CRC tissues being associated with distant metastasis, tumor differentiation, tumor size and advanced TNM staging, low histological grade, later tumor-node-metastasis stage and less OS." (PMID 31632922, 2019). "Studies have found that many lncRNAs, including lncRNA-ROR, MALAT1, and GAS5, can affect tumor development by acting as ceRNAs." (PMID 31186629, 2019). "Multiple studies have proved that GAS5 is dysregulated in human cancers and functions as a tumor suppressing lncRNA." (PMID 30733959, 2019). "LncRNAs known to be a regulatory factor of tumor stem cells included GAS5, NEAT1, SOX2OT, Malat-1, HOTAIR, PVT1, BCAR4 and RBM5-AS1." (PMID 31143372, 2019). "In summary, we identified a tumor suppressing role of GAS5 in HCC invasion by positively regulating RECK expression in a ceRNA manner." (PMID 30733959, 2019). "Seventy-two tumor tissue specimens (39.3%) exhibited a high expression of GAS5, and the other 111 cases (60.7%) had low expression." (PMID 31619268, 2019). "GAS5 acts as a tumor suppressor and is lost in lung cancer and mesothelioma, which is consistent with findings in other cancer types." (PMID 31632972, 2019). "Further, our results showed that GAS5 overexpression constrained cell proliferation, invasion, migration and tumor growth, and also induced apoptosis by regulating miR-106a-5p through the Akt/mTOR pathway." (PMID 31182630, 2019). "In vivo, GAS5 overexpression inhibited tumor growth by negatively regulating miRNA-106a-5p expression." (PMID 31182630, 2019). "GAS5 up-regulation inhibits tumor proliferation, invasion, and migration by regulating related miRNAs, inhibiting EMT processes, activating signaling pathways, and inhibiting cell cycle progression." (PMID 30606744, 2019). "In human CRC tumor tissues, Gas5 has been found downregulated and it is correlated with tumor size, TNM staging, lymph node metastasis, low histological grade and less OS." (PMID 31632922, 2019).
tumor (continued). "Long noncoding RNA (LncRNA) growth arrest-specific 5 (GAS5) has been characterized as a tumor suppressor in numerous kinds of human cancers." (PMID 30733959, 2019). "Of the tumor-suppressive lncRNAs, MEG3 correlated with stage, tumor invasion depth, and tumor size, whereas expression of GAS5 correlated with prognosis." (PMID 30518158, 2018). "The analysis highlighted the significantly improved clinical benefit of the model incorporating GAS5 loss in predicting NMIBC relapse for threshold probabilities ≥25%, compared to the tumour stage, grade and EORTC-risk group model." (PMID 30374124, 2018). "Furthermore, in vitro cloning and functional expression analysis revealed that GAS5 overexpression caused cell cycle arrest, increased apoptosis, as well as inhibited tumor metastatic potential, which could explain the correlation between reduced patient survival and GAS5 level in our study." (PMID 30289954, 2018). "The Gas5 mRNA and protein expression was higher whereas the tumor diameter was smaller and TNM staging was lower." (PMID 29308053, 2018). "Gas5 expression has been reported to be related to clinicopathological characteristics, like tumor size, staging, lymph node metastasis and invasion." (PMID 29308053, 2018). "Multiple ceRNA studies of GAS5 have highlighted its tumor suppressive roles, in particular, through its regulation of the PTEN tumor suppressor gene." (PMID 29702599, 2018). "Gas5 mRNA and protein expression in CRC tissues was associated with tumor size and TNM staging (P < 0.05)." (PMID 29308053, 2018). "It has been reported that GAS5 expression was decreased in cancerous tissues of NSCLC patients as a tumor suppressor; GAS5 suppressed tumorigenesis in NSCLC in vitro and in vivo." (PMID 29367413, 2018). "Gas5 (Growth Arrest-Specific 5) has been first observed by a study that demonstrated a tumor suppression role in 1988." (PMID 29423063, 2018). "Up to 6 weeks after injection, tumors were found in all of mice in pcDNA3.1 group while only one mouse bore a tumor in pcDNA3.1/Gas5 group." (PMID 29423063, 2018). "The tumor suppressor lncRNA GAS5 was significantly under-expressed in the three types of cancer [0.08 (0.006–0.38) in RCC, p <0.001; 0.10 (0.003–0.89) in GB, p < 0.001; and 0.12 (0.015–0.74) in HCC, p < 0.001]." (PMID 30289954, 2018). "Despite the crucial tumour-suppressive role of GAS5 lncRNA in the molecular background of BlCa establishment and progression, there is no complete evaluation of its clinical utility for the patients." (PMID 30374124, 2018). "Significantly lower GAS5 levels (p < 0.001) are expressed in muscle-invasive (T2–T4) and connective tissue-invasive (T1) tumours compared to superficial Ta tumours, as well as in HG tumours related to LG ones (p < 0.001)." (PMID 30374124, 2018). "For example, one of the downregulated RNAs is the growth arrest specific transcript 5 (GAS5), involved in cell proliferation, and its downregulation has been shown to be pro-cancerous in several tumor types." (PMID 30441823, 2018). "Taken together, our study identified a tumor suppressive role of Gas5 in PTC cells acting as a ceRNA, effectively becoming a sink for miR-222-3p, modulating the expression of PTEN, which lead to PTEN/AKT pathway activation and proliferation suppression." (PMID 29423063, 2018). "Among these lncRNAs, GAS5 was recently reported to be a tumor suppressor lncRNA because it has been shown to inhibit HCC proliferation and EMT progression by inhibiting the expression of genes such as vimentin." (PMID 29382035, 2018). "The loss of GAS5 was strongly correlated with unfavourable disease prognostic markers, such as HG carcinomas, as well as muscle-invasive (T2–T4) and T1HG tumours." (PMID 30374124, 2018). "The tumor suppressor lncRNA GAS5 binds to the DNA-binding domain of the glucocorticoid receptor (GR) and competes with DNA glucocorticoid response element (GREs)." (PMID 30680063, 2018).
tumor (continued). "In the present study, for the first time, we have evaluated the clinical value of GAS5 tumour-suppressor lncRNA in improving patients’ prognosis and prediction of disease course." (PMID 30374124, 2018). "Taken together, these results suggested that GAS5 acts as a tumor suppressor via inhibiting ESCC cell proliferation, migration, and invasion." (PMID 29745062, 2018). "GAS5 inhibited tumor development as compared with blank group; however, Vad-Fmk, an inhibitor of inflammasome reversed the inhibition of GAS5." (PMID 29229673, 2018). "GAS1 is a protein coding gene that, similar to GAS5, exerts its tumor suppressor actions through arresting the cell cycle and stimulating apoptosis." (PMID 30289954, 2018). "Here, we have analysed the utility of the GAS5 tumour-suppressor lncRNA in improving BlCa prognosis." (PMID 30374124, 2018). "Expression of GAS5 differed among various localization of tumour and was higher in the right colon compared to left colon and rectum (Kruskal-Wallis: p = 0.0309)." (PMID 30205577, 2018). "Gas5 expression, distant metastasis, tumor differentiation and TNM staging were independent CRC prognostic factors." (PMID 29308053, 2018). "The result showed that patients with low GAS5 expression in cancerous tissues were more prone to high tumor stage." (PMID 29163187, 2017). "Three significantly different expressed genes were verified by RT-PCR, and cell experiment showed interference of GAS5 expression can inhibit the proliferation and metastasis of tumor." (PMID 29296179, 2017). "It has been demonstrated that lncRNA GAS5 acts as a tumor suppressor in NSCLC by targeting and suppressing miR-135b." (PMID 29147648, 2017). "Here, we showed that GAS5 is downregulated not only in tumour tissues but also in the serum of patients with CRC." (PMID 28099146, 2017). "GAS5 is an lncRNA with tumor-suppressive properties: its overexpression sensitizes cancer cells to UV or doxorubicin and decreases tumor proliferation and cell invasion." (PMID 29147648, 2017). "Among these significant differencially expression genes, GAS5 was a common down-regulated genes, and this type of genes was seen as anti-oncogenes, which can affect cell invasion and metastasis in tumor." (PMID 29296179, 2017). "GAS5-001 was widely reported as a tumor-suppressive transcript and GAS5-002 was the longest transcript of GAS5." (PMID 28771526, 2017). "Meanwhile, we found patients with low GAS5 expression in cancerous tissues were more prone to high tumor stage." (PMID 29163187, 2017). "GAS5 has been reported to be down-regulated in multiple cancers, leading to changes in tumor cell production, proliferation, apoptosis, metastasis, and survival time." (PMID 29163187, 2017). "Accordingly, qRT-PCR assay also showed the expression of GAS5-007 in 14 tumor tissue samples was higher than that in 11 normal tissue samples." (PMID 28771526, 2017). "We also highlighted common long non-coding RNA molecules such as HULC, HOTAIR, MALAT1, XIST, H19 and GAS5, which mediate the two-way interactions between stroma and tumor." (PMID 28392501, 2017). "Meanwhile, TCGA analysis also indicated that the expression level of GAS5 was higher in 419 tumor tissue samples than that in 52 normal tissue samples." (PMID 28771526, 2017). "Further, it was found that GAS5 functions as a molecular sponge for miR-21, which is known to promote tumor proliferation and invasion by down-regulating PTEN expression." (PMID 29299178, 2017). "In this study, we focused on a special transcript of GAS5 (ENST00000456293.5, GAS5-007), which was reported as a tumor suppressor." (PMID 28771526, 2017). "Third, aggregated results indicated that decreased GAS5 expression was positively correlated with poor tumor differentiation, larger tumor size, and advanced clinical stage." (PMID 29029523, 2017). "This evidence indicates that GAS5 can act as a common molecular marker for monitoring the effect of chemotherapy in several tumor types." (PMID 29029523, 2017).